Y_RNA (Y RNA )
Gene: Miscellaneous RNA gene on chromosome 12 (112,069,104 to 112,069,209, forward strand). Ensembl gene ENSG00000200688.
Homologues: Orthologues: chimpanzee Y_RNA (97% identical), macaque Y_RNA (92% identical), guinea pig Y_RNA (78% identical), guinea pig Y_RNA (77% identical), guinea pig Y_RNA (75% identical). Paralogues in human: Y_RNA (83% identical), RNY1P5 (82% identical), Y_RNA (81% identical), Y_RNA (79% identical), Y_RNA (78% identical), Y_RNA (77% identical), Y_RNA (76% identical), RNY1 (75% identical), RNY1P1 (75% identical), RNY1P6 (75% identical), Y_RNA (75% identical), Y_RNA (74% identical), and 90 more.